SIGLEC10 (sialic acid binding Ig like lectin 10)
Diseases named in the same sentence as SIGLEC10 in open-access papers (continued):
Sharing a sentence is not in itself a finding about the gene and the disease.
tumor (continued). "The team’s findings suggest that antibodies that block CD24 and Siglec10 interactions can enhance macrophages’ effectiveness in killing tumor cells in refractory ovarian cancer, which is common in women, and triple-negative breast cancer, which is difficult to immunotherapy." (PMID 37484024, 2023). "The novel Nanosphere‐AntiCD24, synthesized by linking nanospheres with CD24 antibody, accurately regulates the degradation of CD24 protein and partially restores the phagocytic function of macrophages toward tumor cells by blocking the CD24/Siglec‐10 signaling pathway." (PMID 36866919, 2023). "In addition, the combination of OAd-Siglec10-Fc with anti-PD-1 significantly enhanced the antitumor effect in a 4T1 tumor model by remodeling the TME." (PMID 38016957, 2023). "Further functional analysis indicated that CD24 degradation mediated by ASGPR‐driven LYTACs affected the signal transmission of the CD24/Siglec‐10 signal pathway, expression of related genes downstream of Siglec‐10 in macrophages, and phagocytosis of tumor cells by macrophages." (PMID 36866919, 2023). "In addition, the expression of Siglec10 and SIRPα had strong associations with macrophages while TIGIT had weak associations with macrophage among almost all tumor types." (PMID 38016957, 2023). "Abnormally high expression of “do not eat me” signaling proteins, binding to macrophage surface related receptors, like SIRPα and Siglec10, can impair relevant signaling in macrophages, leading to reduced macrophage clearance and ineffective immune surveillance against tumor cells." (PMID 37484024, 2023). "In addition, tumor-expressed CD24 promotes immune evasion by interacting with the inhibitory receptor sialic acid-binding Ig-like lectin 10 (Siglec-10) expressed as an anti-phagocytic signal by tumor-associated macrophages (TAMs)." (PMID 38259511, 2023). "However, tumor expressed CD24 in ovarian cancer prevents macrophage-mediated phagocytic tumor clearance and promotes immune evasion by interacting with the inhibitory receptor sialic-acid-binding Ig-like lectin 10 (Siglec-10) expressed on TAMs." (PMID 36035994, 2022). "Finally, the surface receptor CD24 was exclusively expressed on tumor cells and interacts with SIGLEC10 on macrophages in the immune cells." (PMID 35688160, 2022). "Interestingly, tumor cells expressing CD24 may promote immune evasion through its interaction with the inhibitory receptor SIGLEC10 expressed by macrophages." (PMID 38358826, 2024). "This showed that normal B cell subsets express similar levels of surface Siglec‐10 (memory B cells more than naive B cells), and moreover, these surface expression levels on average exceed those of CLL tumor cells." (PMID 37424400, 2023). "Anti-SIGLEC10-mAb prevents the interaction between SIGLEC10 and another “don’t-eat-me” signal CD24, improving TAMs’ phagocytosis of tumor cells." (PMID 37251409, 2023). "Taken together, these data demonstrate that the armed OAd-SIRPα-Fc, OAd-Siglec10-Fc and OAd-TIGIT-Fc can selectively lyse tumor cells and secrete high levels of functional fusion proteins." (PMID 38016957, 2023). "Tumor samples from the PBS, anti-PD-1, OAd-Siglec10-Fc and combination therapy groups collected on day 12 were subjected to RNA-seq." (PMID 38016957, 2023). "The results of this study demonstrated that OAd-SIRPα-Fc, OAd-Siglec10-Fc and OAd-TIGIT-Fc were able to produce SIRPα-Fc, Siglec10-Fc and TIGIT-Fc, respectively, which effectively bound to CD47+, CD24+ and CD155+ tumor cells." (PMID 38016957, 2023). "Tumor cells overexpress anti‐phagocytic ligands CD47, PD‐L1 MHC‐I, and CD24, and can interact with their corresponding receptors SIRPα, PD‐1, LILRB1, and Siglec‐10 on the macrophages and send “don't eat me” signals to evade phagocytic clearance by macrophages." (PMID 37323705, 2022).
tumor (continued). "Since the discovery of the first tumor phagocytosis-related checkpoint, namely the CD47/SIRPα axis, in the late 2000s, other tumor phagocytosis-related checkpoints have been identified: the PD-1/PD-L1 axis, MHC-I/LILRB1 axis, and CD24/SIGLEC-10 axis." (PMID 35978372, 2022). "We found that several pro-tumor markers are increased in cancer tissues, including CD163, CD206, SIRPα, LILRB1, SIGLEC10, AXL, MERTK, and MARCO." (PMID 34778091, 2021). "A significant percentage of tumor‐infiltrating CD8+ and CD4+ T cells expressed Siglec‐10." (PMID 39373395, 2024). "Furthermore, the specific binding of purified SIRPα-Fc and Siglec10-Fc to CD47 or CD24, respectively, enhanced macrophage‐mediated tumor cell phagocytosis in vitro." (PMID 38016957, 2023). "Knockdown of CD24 or Siglec10, as well as using CD24 monoclonal antibodies to block the interaction of CD24 with Siglec10, significantly enhances macrophage phagocytosis of all CD24-expressing human tumor cells." (PMID 37484024, 2023). "In addition, CD24, which is highly expressed in Cancer Cells, synergizes with SIGLEC10 in Dendritic Cells, Macrophages, GMP Cells, B Cells, and Mast Cells to mediate tumor immune escape." (PMID 36401283, 2022). "In addition, the high expression of CD24 in Cancer Cells affects the expression of SIGLEC10 in Dendritic Cells, Macrophages, GMP Cells, B Cells, and Mast Cells, which in turn affects immune disorders and leads to tumor immune escape responses." (PMID 36401283, 2022). "In the gene correlation analysis, clustering results for genes such as B4GALNT1, SIGLEC10, and PSAP further support the idea that these genes may participate in similar biological processes or pathways, particularly those related to inflammation, immune regulation, and tumor progression." (PMID 41445741, 2025). "It is postulated that the secreted SIRPα-Fc and Siglec10-Fc blocked the corresponding “do not eat me” signals and thus restored TAM‐mediated tumor cell phagocytosis." (PMID 38016957, 2023).
cancer (30 papers, 2013 to 2025). A tumor composed of atypical neoplastic, often pleomorphic cells that invade other tissues. "Among them, Sialic acid-binding immunoglobulin-like lectins 10 and 11 (SIGLEC10, SIGLEC11) and Keratin-associated protein 5 (KRTAP5-3) transcripts, genes known to be involved in cancer progression, turned out to be up-regulated only in TPC-1-exo." (PMID 38338696, 2024). "Ablation of either CD24 or Siglec‐10, as well as blockade of the CD24 / Siglec‐10 interaction, is a promising strategy for cancer immunotherapy." (PMID 36794651, 2023). "This confirmed that the targeted degradation of CD24 by Nanosphere‐AntiCD24 affected communication between macrophages and cancer cells through the CD24/Siglec‐10 signaling pathway." (PMID 36866919, 2023). "Phagocytosis checkpoints, including PDCD1, LILRB1, SIGLEC10, and SIRPα are significantly for the function of TAMs in many cancers." (PMID 35317832, 2022). "As an important “don't eat me” signaling molecule, CD24 binds to Siglec‐G (mice) or Siglec‐10 (humans) in cancer cells, triggering the immune escape reactions." (PMID 34363319, 2021). "Then, three-armed cancer-targeting OAds were developed: OAd-SIRPα-Fc and OAd-Siglec10-Fc, which expressed SIRPα-Fc or Siglec10-Fc, respectively, to target macrophages to restore the phagocytic capabilities of these cells, and OAd-TIGIT-Fc, which secreted TIGIT-Fc to reactivate T cells." (PMID 38016957, 2023). "In addition, SIGLEC10 knockout could enhance the phagocytic ability of macrophages towards cancer cells." (PMID 37359556, 2023). "Some cancer cells express “don't eat me” signal ligands such as CD47 and CD24, which can be recognized by TAM receptors such as SIPR1a (for CD47) and SIGLEC10 (for CD24), effectively blocking the attack from TAMs." (PMID 40083710, 2025). "With increased understanding of cancer immunological mechanisms, particularly the role of “don’t eat me” CD24/Siglec10 signaling, we propose that CD24 blockade is a promising strategy for cancer treatment." (PMID 40486886, 2025). "After treatment, cancer cells succumbed to starvation treatment, and the effect of immunotherapy was enhanced by relieving the immunosuppression induced by the CD24/Siglec‐10 pathway." (PMID 36866919, 2023). "In addition, it is suggested that CD24/SIGLEC10 might be a target for cancer immunotherapy." (PMID 35688160, 2022). "Many recent studies have highlighted the role of Siglec‐10 in immune modulation in cancer; however, the crystal structure of Siglec‐10 has not yet been experimentally resolved." (PMID 40667828, 2025). "Noteworthily, the expression of SIRPα, SIGLEC10, and LILRB1 also increased in cancer tissues." (PMID 34778091, 2021). "In fact, circulating autologous CD14+ cells are the progenitor of resident NLCs and the baseline upregulation of Siglec‐10 might reflect the M2‐like immunosuppressive profile of NLCs within TME, where they interact with CD24+ cancer cells, receiving anti‐phagocytic stimuli." (PMID 37654003, 2023).
infection (5 papers, 2013 to 2025). The state of being infected such as from the introduction of a foreign agent such as serum, vaccine, antigenic substance or organism. "CD24 interacted with Siglec‐10 on innate immune cells to dampen damaging inflammatory responses to infection." (PMID 37519221, 2023).
SIGLEC10 also shares sentences with these, for which no sentence is quoted: glioblastoma (2 papers); asthma (1); bacterial infection (1); cervical cancer (1); colon adenoma (1); colorectal (1); coronary aneurysm (1); cutaneous melanoma (1); diabetes (1); gastric cancer (1); immune disorders (1); kidney chromophobe (1); malignant glioma (1); staphylococcus aureus infection (1); stomach adenocarcinoma (1); triple-negative breast carcinoma (1); tuberculosis (1); type 2 diabetes (1).